NLRP3 (NLR family pyrin domain containing 3)
Diseases named in the same sentence as NLRP3 in open-access papers (continued):
Sharing a sentence is not in itself a finding about the gene and the disease.
pneumonia (70 papers, 2013 to 2026). An acute, acute and chronic, or chronic inflammation focally or diffusely affecting the lung parenchyma, caused by an infection in one or both of the lungs (by bacteria, viruses, fungi, or mycoplasma.). "The importance of lung IR inflammation was also demonstrated by the fact that disruption of NLRP3 inflammasome-mediated IL-1β production or sensing was associated with worse bacterial clearance as part of a superimposed pneumonia." (PMID 41467904, 2026). "In summary, the therapeutic use of mMSC-exos can reduce lung inflammation and the phenotype of BMDMs associated with MCMV-induced pneumonia by specifically inhibiting NF-κB/NLRP3 inflammasome signaling." (PMID 38675960, 2024). "In previous studies on mouse models of pneumonia caused by S. aureus, the subcutaneous administration of resveratrol significantly ameliorated S. aureus-induced pneumonia by reducing the NLRP3-mediated inflammation." (PMID 39268247, 2024). "It has been shown to alleviate asthmatic inflammatory cell infiltration and mucus secretion in mouse models by blocking NOD-like receptor thermal protein domain associated protein 3 (NLRP3) inflammasomes and alleviating pneumonia inflammation." (PMID 36120373, 2022). "NLRP3 activation protects the host from infections caused by several pneumonia-causing bacteria such as C. pneumoniae, S. pneumoniae, K. pneumoniae, S. aureus, and L. pneumophila." (PMID 34737734, 2021). "When NLRP3 is activated by α-hemolysin during S. aureus-induced pneumonia, it causes necrotizing pneumonia or necrotic lung injury that is independent of IL-1β signaling." (PMID 34737734, 2021). "Due to a diminished expression and function of NLRP3 in the lungs of an aging population, their susceptibility to secondary pneumonia caused by S. pneumoniae was enhanced." (PMID 34737734, 2021). "Aged mice had decreased NLRP3 expression and function, which made them more susceptible to pneumonia, ALI, and death." (PMID 34737734, 2021). "Decreased expression of NLRP3 also inhibited the onset of severe necrotic pneumonia caused by S. aureus by enhancing bacteria clearance." (PMID 34737734, 2021). "Taken together, these findings indicate that development of pneumonia is accompanied by blockage of autophagy, with NLRP3 and autophagy pathways negatively associated with one another." (PMID 35111047, 2021). "Aged mice exhibit a reduced NLRP3 expression and function, which increases their susceptibility to developing pneumonia, ALI, and mortality." (PMID 32849610, 2020). "For example, α-hemolysin-mediated activation of NLRP3 in a mouse pneumonia model has been linked to IL-1β-independent necrosis, pulmonary damage, and severe pneumonia." (PMID 26617605, 2015). "Nevertheless, it seems that NLRP3 can selectively elicit a protective antibacterial response as exemplified in a S. pneumoniae lung infection model, where NLRP3 deficient mice exhibited higher mortality and increased bacterial loads." (PMID 23666718, 2013). "The NLRP3 inflammasome is a key driver of lung inflammation and has been implicated in several pulmonary conditions that share pathophysiological features with acute lung injury, including pneumonia and acute respiratory distress syndrome (ARDS)." (PMID 40616268, 2025). "Furthermore, silencing of THBS1 can inhibit the activation of the NLRP3 inflammasome, reducing the levels of inflammatory cytokines, thereby reducing pneumonia caused by cytokine storms." (PMID 38424541, 2024). "Previous studies have found that staphylococcal toxins (e.g., α-hemolysin and toxic shock syndrome toxin), could activate NLRP3 inflammasome and cause bacterial toxin infectious diseases, such as pneumonia." (PMID 35051006, 2022). "We emphasize that in the pneumonia caused by CA-SA, the control of inflammation is as important as the anti-infection strategy, and that inhibition of the NLRP3 inflammasome may serve as a mechanism for severe acute S. aureus pneumonia adjuvant therapy." (PMID 35739262, 2022).
pneumonia (continued). "Also, during S. aureus-induced pneumonia, NLRP3 deficiency prevents the onset of severe necrotic pneumonia via promoting bacterial clearance." (PMID 32849610, 2020). "Also, the NLR Family Pyrin Domain Containing 3 (NLRP3) activation in BECs during various pneumonia-causing bacterial (K. pneumoniae, S. pneumoniae, S. aureus, C. pneumoniae, and L. pneumophila) infections protects the host from infections." (PMID 32849610, 2020). "The lower expression and function of NLRP3 in aged immune cells (macrophages, epithelial cells, and DCs) attribute to the increased unfolded protein responses (UPRs), which causes a decreased inflammasome assembly and function increasing the severity of pneumonia caused by S. pneumoniae." (PMID 32849610, 2020). "FZJD mitigates acute pneumonia by dampening macrophage NLRP3 inflammasome activation while restraining neutrophil NETosis." (PMID 41484909, 2026). "In summary, dismantling the NLRP3-NETs feedback loop represents a promising therapeutic strategy for severe pneumonia, and FZJD provides a clinically derived polypharmacological approach to target these mechanisms." (PMID 41484909, 2026). "•Venenum bufonis alleviates RSV-induced pneumonia potentially via suppression of macrophage infiltration and NLRP3 inflammasome activation in the lungs." (PMID 41349590, 2026). "Together, these data indicate that FZJD mitigates pneumonia predominantly through dampening NLRP3 inflammasome activation and curbing NETs formation in the lung tissue." (PMID 41484909, 2026). "Our data indicated that SA significantly inhibited LPS-induced acute pneumonia in mice via up-regulating Nrf2, inhibiting NLRP3 inflammasome and NF-κB activation, and identified Keap1 as the direct target of SA." (PMID 40179791, 2025). "Analysis of pneumonia-related lung injury samples from patients in the Gene Expression Omnibus dataset GSE40012 indicated that NOD-like receptor protein 3 (NLRP3)-mediated pyroptosis was a primary mechanism in ALI." (PMID 39925847, 2025). "Our previous study has demonstrated that DP can protect S. aureus-induced pneumonia probably by suppressing the expression of NLRP3." (PMID 41000417, 2025). "The NF-κB/NLRP3 inflammasome signaling pathways play a critical role in the lung immune response, contributing to both the initiation and progression of pneumonia." (PMID 38675960, 2024). "The NOD-like receptor family pyrin domain containing 3 protein (NLRP3) inflammasome during S. aureus lung infection aggravates severe pneumonia pathology." (PMID 38803378, 2024). "Enzyme‐linked immunosorbent assay (ELISA) was used to detect the levels of tumor necrosis factor‐α (TNF‐α), interleukin (IL)‐1β, NLRP3, and LL‐37 in the sera of healthy subjects, children with KD, and children with pneumonia." (PMID 37773705, 2023). "In this study, phillyrin downregulated the expression levels of Caspase1, ASC and NLRP3 in the lungs of mice with virus-induced pneumonia and reduced the protein ratio of Caspase1p20/Caspase1, thereby inhibiting NLRP3 inflammasome overactivation." (PMID 37957672, 2023). "In our study, the serum levels of TNF‐α, IL‐1β, and NLRP3 were significantly elevated in children with KD and pneumonia compared with healthy subjects." (PMID 37773705, 2023). "In mice models of S. pneumoniae keratitis, the NLRP3 inflammasome (NLRP3, ASC, and caspase-1) was proven to be essential for cleavage and secretion of corneal neutrophil-derived IL-1β and bacterial clearance." (PMID 35655803, 2022). "Concomitantly, our lab reinforced the existence of a fully functional NLRP3 inflammasome in neutrophils in a model of S. pneumoniae-induced pneumonia." (PMID 35406754, 2022). "This has been demonstrated in pneumonia mouse models, in which cytokine production was hindered by the inhibition of NF-κB signaling, NLRP3 inflammasome inhibition, and IL-1R signaling." (PMID 34011681, 2021).
pneumonia (continued). "Taken together, these data demonstrated that the NLRP3 inflammasome was activated in S. aureus-induced pneumonia, accompanied by decreased NEK7 protein levels." (PMID 34603335, 2021). "The aging also increases the susceptibility of the host to secondary S. pneumoniae-induced pneumonia due to the decreased NLRP3 expression and function in the aged lung." (PMID 32849610, 2020). "An experimental study has shown the beneficial effects (inhibition of ALI, decrease in pro-inflammatory cytokines levels, and decrease in the mortality) of resveratrol during K. pneumoniae-induced pneumonia through the NLRP3 inflammasome inhibition." (PMID 32849610, 2020). "The NLRP3-mediated control of K. pneumoniae-induced pneumonia involves the increased neutrophil infiltration, macrophage necrosis, and the release of high-mobility group box-1 protein (HMGB-1)." (PMID 32849610, 2020). "The loss of ADAM10 in the immune cell compartment or global loss of NLRP3 was beneficial to the host in a mouse pneumonia model of S. aureus infection, reducing mortality compared to mice with intact ADAM10 or NLRP3." (PMID 27043625, 2016). "In order to examine the effect of NLRP3 on lung barrier function during pneumonia, mice were intranasally infected for 24 h with a S. pneumoniae serotype 3 strain (PN36)." (PMID 27476670, 2016). "Taken together, these data indicate that the P2X7R expression on neutrophils is required for NLRP3 inflammaomse activation and bacterial killing in S. pneumoniae corneal infection." (PMID 26877061, 2016). "Here we show that NLRP3 protects the integrity of the alveolar barrier in a mouse model of Streptococcus pneumoniae-induced pneumonia, and ex vivo upon treatment of isolated perfused and ventilated lungs with the purified bacterial toxin, pneumolysin." (PMID 27476670, 2016). "CE reduced pro-inflammatory cytokine secretion, inhibited NLRP3, Caspase-1, and IL-1β protein expression, and upregulated key autophagy genes and proteins, thereby promoting autophagy and subsequently alleviating Hp-induced pneumonia damage in chicks." (PMID 41092609, 2025). "Strong protective effect against LPS-induced pneumonia in mice by inhibiting TLR4/NF-JB/NLRP3." (PMID 39889188, 2025). "This study indicates that SA might be a new covalent molecule of Keap1 to activate Nrf2, and is a promising drug candidate or lead molecule for the therapy of acute pneumonia through regulating Nrf2/NF-κB/NLRP3 inflammasome axis." (PMID 40179791, 2025). "Above all, SA attenuated acute pneumonia by regulating of Nrf2, NF-κB and NLRP3 inflammasome." (PMID 40179791, 2025). "Additionally, BBR alleviated influenza virus-induced pneumonia by suppressing NLRP3 inflammasome and reducing mitochondrial reactive oxygen species production." (PMID 40736123, 2025). "Another study could show that the deletion of Terc in mice resulted in NLRP3 inflammasome activation after infection with S. aureus, thus contributing to more severe pneumonia." (PMID 39607755, 2024). "Notably, the mRNA and protein expression levels of Caspase1, ASC and NLRP3 were all elevated in the lungs of mice with H1N1-induced pneumonia, but these trends were suppressed in the phillyrin group." (PMID 37957672, 2023). "The NLRP3/caspase-1 pathway is crucial to PM2.5-induced pneumonia." (PMID 37215119, 2023). "Moreover, phillyrin also inhibited the mRNA and protein expression levels of Caspase1, ASC and NLRP3 in the lungs of mice with H1N1-induced pneumonia." (PMID 37957672, 2023). "PVL exposure activates NLRP3, and binding to monocytes and macrophages leads to the release of the caspase-1-dependent pro-inflammatory cytokines IL-1β and IL-18, which induce macrophage death and exacerbate pneumonia." (PMID 35878202, 2022). "Importantly, pneumonia still occurred in mice after NLRP3 KO, suggesting that poststroke pneumonia primarily depends on peripheral immunosuppression rather than NLRP3 activation in the lung itself." (PMID 35432726, 2022).
pneumonia (continued). "PVL is an important virulence factor for the induction of apoptosis, acting on NLRP3 to induce macrophage death and IL-1β secretion during the course of pneumonia disease; PVL induces the release of the apoptotic proteins cytochrome c and Smac/DIABLO in mitochondria." (PMID 35878202, 2022). "Moreover, we demonstrated a significant role of SAK in ST398 infection-induced acute pneumonia model, which is mainly achieved by activating innate immune signals, especially NLRP3 inflammasome-related pathways." (PMID 35739262, 2022). "Beta-toxin, gamma-hemolysin, PVL, and Hla (166, –, 168) trigger the NLRP3 inflammasome in macrophages, monocytes, and neutrophils, resulting in proinflammatory IL-1β and IL-18 secretion that is responsible for necrotic injuries and severe pneumonia in vivo." (PMID 34011681, 2021). "Finally, while investigating the possible beneficial effects of this sterile lung IR inflammatory response, we determined that the presence of NLRP3-dependent lung IR inflammation was able to reduce the bacterial burden created by an experimental pneumonia." (PMID 29163464, 2017). "In the future, therapeutic stimulation of NLRP3 might be useful to stabilize the lung barrier function during pneumonia." (PMID 27476670, 2016). "We have previously demonstrated that the amino acid polymorphisms TLR5-1205C/T, NLRP3-2906A/G, and NOD2-2197A/C in PRRs in pigs, which have been shown to alter pathogen recognition and cytokine production at the cellular level, are also associated with pneumonia severity in commercial pig farms." (PMID 39202462, 2024). "Moreover, the elevation of TNF‐α, IL‐1β, and NLRP3 was more pronounced in KD than in children with pneumonia, which may be related to the storm of inflammatory factors triggered by immune imbalance in KD." (PMID 37773705, 2023). "Taken together, we speculate that SAK exacerbates CA-SA-induced pneumonia by promoting NLRP3 inflammasome activation, providing new insights into the pathogenesis of highly virulent CA-SA and emphasizes the importance of controlling inflammation in acute pneumonia." (PMID 35739262, 2022). "SARS-CoV-2 binding to ACE2, and Ang II-induced activation of AT1R, and activation of complement pathways by SARS-CoV-2 may induce assembly of the NLRP3 inflammasome, which contributes to the onset of cytokine storm, pneumonia, ARDS, thrombosis, DIC, and other types of organ dysfunction." (PMID 34177896, 2021). "Consequently, promotion of autophagy to degrade NLRP3 may be an effective therapeutic strategy for preventing and treating S.pn-induced pneumonia." (PMID 35111047, 2021). "In conclusion, we found that the upregulation of the NLRP3 inflammasome was associated with MRSA infection secondary to IAV, but that MRSA superinfection resulted in a decrease in the expression of IL‐1β someway, by which impair the host immunity and lead to aggravated pneumonia." (PMID 32697385, 2020). "Therefore, we designed experiments to reveal whether Rhein can treat RSV-induced pneumonia by inhibiting NLRP3 inflammasome activation." (PMID 32047436, 2019). "The results revealed that Vb treatment significantly suppressed mRNA levels of NLRP3, Caspase-1, and IL-1β in lung tissues of RSV-infected mice with pneumonia." (PMID 41349590, 2026). "We collected sera from healthy physical examiners, children with KD, and children with pneumonia and measured the levels of TNF‐α, IL‐1β, NLRP3, and LL‐37 in serum." (PMID 37773705, 2023). "In a study on pneumonia, Maxing Shigan decoction (MXSG) was found to have a similar effect as the NLRP3 inhibitor INF39 and to downregulate NLRP3 expression and reduce IL-1β and IL-18 secretion." (PMID 35411030, 2022). "Second, 4D label-free proteomics analysis showed that suppression of NLRP3 expression and repair of autophagy played pivotal pharmacological roles in QFY pneumonia therapy." (PMID 35111047, 2021).
pneumonia (continued). "In addition, we used a selective small-molecule NLRP3-inflammasome inhibitor MCC950, to verify NLRP3 activation in the role of MHV68 pneumonia." (PMID 37704783, 2023). "Therefore, based on the molecular docking results, the present study hypothesized that baicalin, as a lead compound, may play a role in mitigating P. multocida-induced pneumonia and vascular inflammatory injury by inhibiting the dual targets COX-2 and NLRP3." (PMID 41153980, 2025). "This study demonstrates that phillyrin can ameliorate pulmonary inflammation in mice with virus-induced pneumonia, and its anti-inflammatory mechanisms may be through antagonizing CXCR2 and suppressing NLRP3 inflammasome overactivation in the lung of infected mice." (PMID 37957672, 2023). "Moreover, phillyrin inhibited the mRNA and protein expression levels of Caspase1, ASC and NLRP3 in the lungs of mice with H1N1-induced pneumonia.This study reveals that phillyrin ameliorates IAV-induced pulmonary inflammation by antagonizing CXCR2 and inhibiting NLRP3 inflammasome activation partly." (PMID 37957672, 2023). "Thus, therapeutic targeting of NLRP3, NLRC4, and NLRP4 inflammasome during Gram-positive bacteria-induced severe pneumonia responsible for ALI may prove beneficial to the host." (PMID 32849610, 2020). "Genetic deletion of NLRP3 improved clinical parameters in mouse pneumonia without effecting pathogen burden, suggesting that blunting the inflammasome mediated inflammatory response to S. aureus could be beneficial even after infection is established." (PMID 27043625, 2016).